BRCA2 (BRCA2 DNA repair associated)
Diseases named in the same sentence as BRCA2 in open-access papers (continued):
Sharing a sentence is not in itself a finding about the gene and the disease.
breast cancer (continued). "For the breast cancer cells, increased BRCA2 protein levels were first observed after 4–8 h of I3C (60 μM); while increases in BRCA1 levels were detected earlier, but were relatively small in magnitude at early time points." (PMID 16434996, 2006). "Approximately 5% of all cases of breast cancer are associated with inherited predisposition syndromes and about half of these are attributable to mutations in the BRCA1 and BRCA2 genes." (PMID 16538216, 2006). "The breast cancer risk by age 70 years was estimated to be 72% in BRCA1 mutation carriers and 75% in BRCA2 mutation carriers." (PMID 16417652, 2006). "There was evidence that increasing number of live births was associated with a decreasing risk of breast cancer in BRCA1 and BRCA2 mutation carriers combined." (PMID 17187672, 2006). "Germ-line mutations in genes such as BRCA1, BRCA2, and ATM can cause a substantial increase in risk of breast cancer." (PMID 16945136, 2006). "In contrast, we found evidence that increasing parity was protective among both BRCA1 and BRCA2 mutation carriers, and that BRCA1 mutation carriers with two or more offspring had a significantly lower breast cancer risk." (PMID 17187672, 2006). "Shortly after the cloning of the breast cancer susceptibility genes BRCA1 and BRCA2, three specific mutations in BRCA1 and BRCA2 were found to be 20 times more common in individuals of Ashkenazi Jewish descent than in the general population." (PMID 17102813, 2006). "All participants had a high quantitative breast cancer risk, defined as ≥ 3.5% over the next 5 years per the Gail or BRCAPRO models, and/or a known BRCA1 or BRCA2 germline mutation." (PMID 16800895, 2006). "Various reproductive factors have been shown to exert different effects on the risk of breast cancer among BRCA1 and BRCA2 mutation carriers." (PMID 16563180, 2006). "Against these, however, are data showing that incidence of breast cancer in BRCA1 and BRCA2 mutation carriers is altered by endocrine risk modifiers such as pregnancy." (PMID 16538216, 2006). "We showed that two phytochemicals with potential cancer prevention activity, I3C and genistein, each upregulate expression of the BRCA1 and BRCA2 breast cancer genes." (PMID 16434996, 2006). "The Tyrer-Cuzick algorithm was applied to the cohort to test its ability to predict future breast cancer and positive BRCA1 or BRCA2 mutation tests, with considerable success." (PMID 16507150, 2006). "Both alleles, BRCA2 (N372H) and ERBB2 (V655I), have been associated with different risk of developing breast cancer." (PMID 16438707, 2006). "A large proportion of familial breast cancer (<40%) can be attributed to mutations in the high-risk genes BRCA1 and BRCA2." (PMID 16762046, 2006). "With regard to individual markers, the most striking difference between BRCA1 and BRCA2 hereditary breast carcinomas was in expression of cell cycle proteins." (PMID 16595007, 2006). "Conversely, plans published after 2000 provide more information on genetic testing for inherited breast cancer susceptibility (BRCA1 and BRCA2 genes) as well as brief discussions of familial risk assessment." (PMID 15888219, 2005).
breast cancer (continued). "In a study of familial and sporadic human breast cancers by Hedenfalk and co-workers, Storey and Tibshirani estimated 33% of the genes to be differentially expressed between BRCA1 and BRCA2 mutation positive tumors." (PMID 16018805, 2005). "In this context, and particularly in highrisk families, the most important tumor suppressor genes associated with breast cancer are BRCA1 and BRCA2." (PMID 16389418, 2005). "To evaluate further the evidence for an association between AR CAG repeat length and breast cancer risk in BRCA1 and BRCA2 mutation carriers, we genotyped the polymorphism in a large series of female mutation carriers." (PMID 15743497, 2005). "Several studies have been undertaken to assess the role of the CAG repeat polymorphism as a modifier of breast cancer risk in BRCA1 and BRCA2 mutation carriers." (PMID 15743497, 2005). "Nipple aspiration was performed on 33 high-risk women (defined as having a 5-year Gail model index of more than 1.7, a personal or family history of breast cancer, and/or a BRCA1 or BRCA2 germline mutation) to identify ductal orifices for lavage procedures." (PMID 16280052, 2005). "In a Finnish study, it was noted that BRCA1 breast cancer patients had a lower survival rate than sporadic cases, BRCA2 patients or patients with non BRCA1/2 related familial breast cancer." (PMID 15996267, 2005). "There is accumulating evidence, both epidemiological and histological, that tumours arising as a result of mutations in the two breast cancer susceptibility gene families (BRCA1 and BRCA2) are biologically distinct." (PMID 15714204, 2005). "When hereditary predisposition to breast cancer is being assessed, it is important to consider the impact of the age-related penetrance of the BRCA1 and BRCA2 genes." (PMID 16079000, 2005). "Only two studies have evaluated the association between anthropometric risk factors or physical activity and the risk of breast cancer in BRCA1 and/or BRCA2 carriers." (PMID 16168130, 2005). "The 5 year breast cancer risk for this patient as calculated by the BRCAPRO model was 5.7%, and her probability of being a BRCA1 or BRCA2 carrier was 0.47." (PMID 15955237, 2005). "The inheritance of a deleterious mutation in either of the two breast cancer susceptibility genes, BRCA1 or BRCA2, has been associated with a lifetime risk of breast cancer of 45% to 87%." (PMID 16168130, 2005). "The model predicts that among women who develop breast cancer at age 30 years, approximately 10% carry a BRCA1 or a BRCA2 mutation." (PMID 15381934, 2004). "Testing the combinatorial effects of Rb loss and other breast cancer mutations (e.g., BRCA1 and BRCA2), along with the further characterization of WAP-T121 tumors, should help provide additional insights into human breast cancer biology." (PMID 14966529, 2004). "By comparison, the predictions under the BRCAPRO model are 3.7% and 0.6% for BRCA1 and BRCA2, respectively, for cases diagnosed under age 36 years and 1.8% and 0.4% for breast cancers diagnosed between ages 36 and 45 years." (PMID 15381934, 2004). "In conclusion, by studying the expression of 47 genes previously identified as candidate prognostic markers in breast cancer, we identified a three-gene expression signature (BRCA2, DNMT3B and CCNE1) with prognostic significance." (PMID 15606925, 2004). "This link between BRCA2 overexpression and poor outcome should be taken into account when evaluating future BRCA2-based therapeutic approaches to breast cancer." (PMID 15606925, 2004). "Invasive lobular BC is seen in 4% of BRCA1-related breast cancer and 4% of sporadic controls, whereas 11% of BRCA2-related breast cancer is of this subtype." (PMID 14735197, 2004).
breast cancer (continued). "In conclusion, the present study demonstrates that 30 μM resveratrol can increase expression of the BRCA1 and BRCA2 oncosuppressors, involved in the aggressiveness of human breast cancer cell lines." (PMID 12838319, 2003). "In contrast to normal breast epithelial cells, BRCA1 mRNA levels in tumours appeared to be downregulated by methylation, while BRCA2 showed significant overexpression in sporadic breast cancers." (PMID 12838319, 2003). "The prevalence of breast cancer is similar for BRCA1 and BRCA2 mutation families (average 3.7 and 3.6 per family), but the former have a much greater risk of ovarian cancer (average 1.5 and 0.6 per family, respectively)." (PMID 12698193, 2003). "The male breast cancer cases were divided into two groups according to their BRCA2 status and CYP17 genotype frequencies compared between them." (PMID 12644832, 2003). "Others have shown that steady-state BRCA1 mRNA levels are elevated in response to oestrogens in human breast cancer cells, and that BRCA2 expression is also regulated by oestrogens in human breast cancer cell lines." (PMID 12838319, 2003). "Of the breast cancer susceptibility genes which have been identified to date, BRCA1 and BRCA2 are the most important ‘high risk’ genes accounting for the majority of families with multiple cases of breast and ovarian cancer." (PMID 11857015, 2002). "There was also significant evidence for a modifying effect of other genes on the risks of breast cancer in BRCA1 and BRCA2 mutation carriers." (PMID 11857015, 2002). "The estimated breast cancer incidence rates for BRCA1 increase up to the age group 40–49 years but then decrease, while the incidence rates for BRCA2 mutation carriers increase with age." (PMID 11857015, 2002). "Out of all breast cancer patients 2% have a strong genetic predisposition, caused by highly penetrant genes (BRCA1 and BRCA2)." (PMID 12454765, 2002). "The resulting model provides a framework for risk estimation to counsel women with a family history of breast cancer, allowing one to estimate carrier probabilities (separately for BRCA1 and BRCA2) and incidence rates in the same analysis." (PMID 11857015, 2002). "The breast cancer risk by age 70 years, based on the average incidence over all modifiers was estimated to be 35.3% for BRCA1 and 50.3% for BRCA2." (PMID 11857015, 2002). "Breast cancer susceptibility genes BRCA1 and BRCA2 are tumour suppressor genes the alleles of which have to be inactivated before tumour development occurs." (PMID 11710835, 2001). "Estimates of the contribution of BRCA1 and BRCA2 to breast cancer incidence in outbred populations have been based on studies that are either small or have selected for cases diagnosed at an early age." (PMID 11044354, 2000). "Breast cancer penetrance by age 80 was estimated to be 48% (95% CI 7–82%) for BRCA1 mutation carriers and 74% (7–94%) for BRCA2 mutation carriers." (PMID 11044354, 2000). "We investigate allelic losses in microsatellites of the RAD51, RAD52, RAD54, BRCA1 and BRCA2 regions, and their correlations with nine pathologic parameters in 127 breast carcinomas." (PMID 10507777, 1999). "Of 268 Ashkenazi Jewish women with sporadic breast cancer, tested in an unrelated study, 16 carried either the 185delAG mutation of BRCA1 or the 6174delT mutation of BRCA2." (PMID 9743298, 1998).
breast cancer (continued). "Germline BRCA1 and BRCA2 mutations enable targeted therapies in human epidermal growth factor receptor 2 (HER2)-negative advanced breast cancer (ABC)." (PMID 41965791, 2026). "Risk factors for breast cancer include age, family history, inherited gene mutations (such as BRCA1 and BRCA2), hormonal factors (early puberty, late menopause, hormone replacement therapy), obesity, alcohol consumption, and exposure to endocrine‐disrupting chemicals such as BPA." (PMID 41201099, 2026). "A large prospective study comparing early-onset breast cancer patients with BRCA1/BRCA2 germline mutations to those with sporadic cancer found no significant survival difference." (PMID 40841483, 2026). "The strongest evidence favoring platinum-based/FOLFIRINOX strategies involves homologous recombination repair deficiency (HRD), especially alterations in germline breast cancer gene 1/2 (BRCA1/2) or partner and localizer of BRCA2 (PALB2), as well as broader genomic scar signatures." (PMID 42193022, 2026). "Before the development of breast cancer, PD-1+ immune cells in carriers with BRCA1 and BRCA2 germline mutations are preferentially localized near the epithelial tissue, which might be associated with early immune evasion in the malignant epithelial tissue." (PMID 40830526, 2025). "Furthermore, investigations have strongly linked single-nucleotide polymorphisms (SNPs) in canine BRCA1 (specifically in intron 8 and exon 9) and BRCA2 (in exon 24 and exon 27) to the development of mammary tumors in dogs." (PMID 41227463, 2025). "Importantly, research conducted by CIMBA recognizing some of these variants as modifiers of breast cancer risk in carriers of BRCA1 and BRCA2 pathogenic variants." (PMID 40296163, 2025). "Therefore, the overall prevalence of germline BRCA1 and BRCA2 carriers among Brunei breast cancer patients were 0% and 5%, respectively." (PMID 40531958, 2025). "Similar to BRCA1 and BRCA2 PV carriers, breast cancers do occur at a young age in women with PJS." (PMID 40317347, 2025). "R/M breast cancer more frequently harbored alterations in BRCA2, ATRX, and ATM (p<0.05)." (PMID 40182039, 2025). "Our study is limited by lack of knowledge as to how the status of P/LP BRCA1 and BRCA2 variants impacted treatment of individual patients with breast cancer or how many patients took advantage of cascade testing." (PMID 40952741, 2025). "This was largely driven by the increased incidence of TNBC which accounted for 56% of BRCA1 carriers with T1N0 breast cancer (90% of whom received chemotherapy), while only 15.6% of BRCA2 and 40% of PALB2 carriers had T1N0 TNBC (of which 80% and 100% received chemotherapy, respectively; eTable 1)." (PMID 40275390, 2025). "In the context of breast cancer, the mutations of BRCA1 and BRCA2 genes could exert an important impact on the ovarian function." (PMID 41153822, 2025). "BRCA2 mutations are the most frequently implicated mutations, accounting for up to 15% of MBC cases, with carriers facing an 8% lifetime risk of developing breast cancer." (PMID 41502531, 2025). "One BRCA2 variant carrier reported a second‐degree family history for cervical cancer and potential ovarian cancer, and one FANCM variant carrier reported a second‐degree family history of breast cancer." (PMID 39440754, 2025). "We found that 16.8% (95% CI, 11.1%-23.9%) of participants with MpBC who underwent germline testing had PGVs in breast cancer susceptibility genes, with PGVs seen across MpBC subtypes and with most PGVs occurring in BRCA1 (11.9% variant prevalence) and BRCA2 (3.5%)." (PMID 39964682, 2025).
breast cancer (continued). "The next step was to decide whether these similarities depended on mutations in the breast cancer susceptibility genes, BRCA1 or BRCA2, by comparisons to sporadic breast cancers." (PMID 39885374, 2025). "Metachronous PDAC after breast cancer is a rare but serious occurrence, typically linked to hereditary predisposition syndromes involving pathogenic variants in homologous recombination repair (HRR) genes such as BRCA2, PALB2, and ATM." (PMID 41229501, 2025). "Therefore, there are no data on the contribution of large rearrangement of BRCA1and BRCA2 in the Brunei breast cancer population presented in this report." (PMID 40531958, 2025). "BRCA1 and BRCA2 carriers without prior breast cancer have the option to undergo risk-reducing mastectomy (RRM)." (PMID 40728683, 2025). "A previous study in Qatar evaluated the impact of BRCA1 and BRCA2 pathogenic mutations on breast cancer aggressiveness in carriers versus non-carriers, involving 82 women diagnosed with breast cancer at the age of 50 or younger." (PMID 41463058, 2025). "For BRCA2, we were not able to perform the comparison because BRCA2 mutation frequency is not established in Polish women with unselected breast cancer." (PMID 40770660, 2025). "Breast cancer is the most common malignancy among women worldwide, with 5–10% of cases attributable to hereditary predisposition, primarily due to pathogenic variants in the BRCA1 and BRCA2 genes." (PMID 41302125, 2025). "In male breast cancer, BRCA2/RAD51C hypermethylation in ~30% of cases suggests PARPi potential." (PMID 40864792, 2025). "The role of germline copy number variants (CNVs) as breast cancer risk modifiers in women carrying BRCA1 and BRCA2 P/LP variants remains relatively unknown." (PMID 39858629, 2025). "Brunei BRCA2 carriers were found to be more likely to have family history of breast and/or ovarian cancer and have ≥1 affected family members in the first-degree with breast cancer (p = 0.027 and p = 0.001 respectively)." (PMID 40531958, 2025). "BRCA1-associated breast cancers tended to be earlier onset at diagnosis (p = 0.003), and when invasive, were higher grade (p < 0.001), node-negative (p = 0.01), and more commonly TNBC (%TNBC: 69.4% BRCA1 vs. 24.7% BRCA2 vs. 31.6% PALB2; p < 0.001)." (PMID 40275390, 2025). "According to the guidelines of the American Society of Clinical Oncology (ASCO) and the European Society of Medical Oncology (ESMO), the most significant genetic factor in the diagnosis and treatment of breast cancer is the mutation status of the BRCA1 and BRCA2 genes." (PMID 40724954, 2025). "Specifically, breast cancers in patients with BRCA1 mutations tend to exhibit a benign appearance and display more circumscribed margins and rim enhancement compared to those with BRCA2 mutations." (PMID 40942929, 2025). "The cumulative risk of developing breast cancer at age 70 is 51–75% with a median age of onset of 40 years for patients with the BRCA1 mutation, and 33–55% with a median age of onset of 43 years for patients with the BRCA2 mutation." (PMID 40142718, 2025). "While most breast cancer cases are sporadic, approximately 10% are attributable to genetic mutations, including those in the breast cancer gene 1 (BRCA1) and breast cancer gene 2 (BRCA2)." (PMID 39997609, 2025). "PARP inhibitors such as olaparib and talazoparib have been approved for unresectable/recurrent breast cancer with germline BRCA1 or BRCA2 (BRCA1/2) mutations and without HER2 expression." (PMID 40861716, 2025).